SNORA74 (Small nucleolar RNA SNORA74 )
Gene: Small nucleolar RNA gene on chromosome 12 (42,347,061 to 42,347,214, reverse strand). Ensembl gene ENSG00000252917.
Homologues: Orthologues: chimpanzee SNORA74 (98% identical), mouse Gm55013 (54% identical), zebrafish SNORA74 (42% identical), zebrafish SNORA74 (38% identical). Paralogues in human: SNORA74D (80% identical), SNORA74A (47% identical), SNORA74C-1 (45% identical), SNORA74C-2 (45% identical), SNORA74B (43% identical), SNORA74 (41% identical), SNORA74 (37% identical), SNORA74 (36% identical).